CTLA4 (cytotoxic T-lymphocyte associated protein 4)
Diseases named in the same sentence as CTLA4 in open-access papers (continued):
Sharing a sentence is not in itself a finding about the gene and the disease.
melanoma (continued). "Combination checkpoint inhibition of PD-1 with CTLA-4 has been evaluated in melanoma, leading to a higher rate of objective response, progression free survival (PFS) and marginally overall survival (OS) than with anti-PD-1 alone, albeit with greater levels of toxicity." (PMID 29805749, 2018). "Indeed, anti-CTLA-4 mAb treatment failed in germ-free or antibiotic-treated sarcoma, melanoma, and CRC mouse models." (PMID 30004433, 2018). "In this scenario, both men and women receive a benefit from CTLA-4 blockade in melanoma." (PMID 30545122, 2018). "Furthermore, grade 3 or 4 enterocolitis is mainly documented in IO/IO combination approaches (anti-CTLA-4 plus anti-PD-1 antibodies) illustrated in checkmate 063 in advanced melanoma in up to 13% of patients." (PMID 29983828, 2018). "Immune checkpoint inhibitors, including anti-CTLA4, anti-PD-1, and anti-PD-L1 antibodies, are effective as single agents in immune-sensitive cancers like melanoma, renal cell carcinoma and NSCLC, but lack efficacy in immune-quiescent or resistant cancers such as pancreatic cancer." (PMID 29385739, 2018). "Furthermore, it has been demonstrated that an increased frequency of ICOS+ CD4+ T cells, sustained over a period of 12 weeks of anti-CTLA-4 therapy, correlates with improved OS in melanoma patients." (PMID 29494517, 2018). "With respect to the checkpoint inhibitors, ipilimumab which targets T cell CTLA-4, was the first agent in this class to show an improved OS in melanoma, and meta-analysis of pooled data from ipilimumab trials which included 1861 melanoma patients revealed a 3-year OS rate of 22%." (PMID 29943192, 2018). "In addition, it has been reported that melanoma patients who experienced clinical benefit from CTLA-4 blockade had a higher degree of richness and evenness in their TCR repertoire than patients who did not have clinical benefit." (PMID 29494517, 2018). "However, anti-CTLA-4 resulted in a similar benefit in men and women when the analysis was restricted to the 4 studies on melanoma (HR 0.67, 95% CI 0.50–0.90, p = 0.008 and HR 0.80, 95% CI 0.68–0.94, p = 0.006, respectively)." (PMID 30545122, 2018). "Ipilimumab is a mAb against CTLA-4 that was approved by FDA for melanoma in 2011." (PMID 30366424, 2018). "CTLA-4 blockade causes a broad enhancement of immune responses and the systemic delivery of anti-CTLA-4 blocking antibodies is currently FDA approved for the treatment of melanoma and renal cell carcinoma." (PMID 30619273, 2018). "For example, patients with melanoma or prostate cancer exhibited upregulation of the inhibitory receptor V-domain Ig suppressor of T cell activation (VISTA) on various tumor-infiltrating immune cells after anti-CTLA-4 treatment." (PMID 29644214, 2018). "Tremelimumab is another anti-CTLA-4 monoclonal Antibody tested inmetastatic melanoma patients." (PMID 29552325, 2018). "This review examines the mechanisms of action and the limitations of anti-PD-1/PD-L1 and anti-CTLA-4 antibodies which are the two types of checkpoint inhibitors currently available to patients and further explores the future avenues of their use in melanoma and other cancers." (PMID 29644214, 2018). "For example, Ipilimunab, an IgG1 antibody-based melanoma treatment, is a T cell potentiator that blocks CTLA-4 to stimulate T cell proliferation and stem malignant disease progression by delaying tumor progression and has been shown to significantly increase life expectancy." (PMID 29701673, 2018). "Clinical outcome of anti-CTLA-4 treatment in melanoma patients correlates with low expression of TIM-3 on circulating T and NK cells prior to and during therapy, and correlates with an increased frequency of mature circulating CD3−CD56dimCD16+ NK cells during treatment." (PMID 30250471, 2018).
melanoma (continued). "Further mechanisms related to host–tumor interactions and their influence on immune checkpoints resistance have been elucidated through the analysis of a cohort of longitudinal tissues from N = 56 melanoma patients treated with anti-CTLA-4 mAb and subsequently, upon progression, with anti-PD-1 mAb." (PMID 30004433, 2018). "Statistical analysis performed on data obtained from all investigated melanoma and hematological cancer cells showed significant (p < 0.05) differences in levels of CTLA-4 and PD-1 expression detected after guadecitabine and DAC treatment, but not after AZA, compared to untreated cells." (PMID 30581389, 2018). "Notably, combined checkpoint blockades involving PD-1 or CTLA-4 demonstrated significantly enhanced efficacy against advanced-stage melanoma, relative to targeting each alone." (PMID 30191140, 2018). "CTLA-4 antagonist, Ipilimumab has been approved in treatment of melanoma and breast cancer." (PMID 29587679, 2018). "The approval of anti-cytotoxic T-lymphocyte-associated protein 4 (CTLA-4) and anti-programmed cell death protein 1 (PD-1) antibodies for human use has already resulted in significant improvements in disease outcomes for various cancers, especially melanoma." (PMID 29644214, 2018). "CTLA-4 mAb lost its therapeutic efficacy against established melanomas, colon cancers, and sarcomas in mice that were reared under germ-free conditions or that had been raised in specific pathogen-free environment and then treated with multiple broad-spectrum antibiotics to sterilize the gut." (PMID 29482595, 2018). "The genetic basis for clinical response to anti-CTLA-4 in melanoma have been recently elucidated." (PMID 30545122, 2018). "For example, two clinical trials have demonstrated that treatment of patients with advanced melanoma using anti-CTLA-4 (ipilimumab) could lead to durable responses and improve the overall survival of patients." (PMID 30115069, 2018). "Comparison of PBMC profiles from melanoma patients treated with anti-PD-1 or anti-CTLA-4 showed distinct frequencies of immune cell subsets that may serve as predictive biomarkers." (PMID 29968076, 2018). "Moreover, it has been demonstrated that T cells response to NY-ESO-1 antigen correlates with the patients’ clinical benefit in melanoma treated with anti-CTLA-4 antibody." (PMID 30108590, 2018). "Current treatment strategies for high-stage melanoma are based around the use of immunotherapy with immune checkpoint inhibitors such as anti-PDL1 or anti-CTLA4 antibodies to stimulate anti-cancer T cell responses, or signal-transduction inhibitors such as those targeting BRAF and MEK pathways." (PMID 29776373, 2018). "Administration of DCs electroporated with TriMix mRNA and a melanoma antigen (gp100, tyrosinase, MAGE-A3 or MAGE-C2 fused to DC.LAMP) demonstrated durable clinical benefit in clinical trials involving patients with advanced melanoma when combined with the CTLA-4 inhibitor ipilimumab." (PMID 30349530, 2018). "Consistent with a different immunomodulatory activity between investigated DHAs, treatment of CTLA-4-positive melanoma cells with guadecitabine, DAC or AZA up-regulated (FC ≥2) the constitutive expression levels of CTLA-4 in 42.8% (3/7), 71.4% (5/7) and 28.6% (2/7) melanoma cell lines, respectively." (PMID 30581389, 2018). "Several studies of CTLA-4 and PD-1 therapy have revealed that BRAF V600E mutations do not correlate with either the response to CTLA-4 therapy or the resulting OS, whereas the correlation with the response of melanomas to PD-1 therapy was significant." (PMID 30073150, 2018). "Likewise, combination of an anti-MARCO with an anti-CTLA4 antibody was investigated in mouse model of melanoma." (PMID 30577495, 2018).
melanoma (continued). "We used an unbiased proteomic microarray approach to compare global antibody levels in pre-treatment sera from melanoma patients treated with anti-CTLA-4, anti-PD-1, or the combination, and identified sets of toxicity-associated antibodies for each of the three treatment cohorts." (PMID 29606147, 2018). "In March 2011, ipilimumab (anti-CTLA-4) was approved by FDA for treatment of advanced melanoma." (PMID 30105035, 2018). "Cytokine-based treatment (e.g., interferon [IFN], IL-2) only induced durable responses in a small fraction of both metastatic RCC and melanoma patients (However, checkpoint inhibitors targeting CTLA-4 and PD-1 have achieved durable responses in patients who were refractory to other therapies." (PMID 29996914, 2018). "Furthermore, we tested if karonudib impaired the anti-tumor effect of anti-CTLA-4 treatment in immunocompetent mice bearing mouse melanoma tumors." (PMID 30042422, 2018). "Antibodies to human CTLA-4 have been shown to induce long-lasting protection against melanoma." (PMID 29713453, 2018). "The rationale of using anti-CTLA-4 antibody in the treatment of melanoma is based on the general concept that tumor immunotherapy may eventually promote tumor growth as consequence of incorrect and prolonged immune response." (PMID 29371600, 2018). "We can hypothesize that tumor- and/or patient-specific factors other than gender may influence response to anti-CTLA-4 agents in melanoma." (PMID 30545122, 2018). "It is possible that patients in C6-KIRC/KIRP may respond to immunotherapeutics such as anti-PD1/PDL1 and anti-CTLA4 which are promising strategies in treatment of advanced melanoma and other tumor types." (PMID 28489584, 2017). "Furthermore, immunomodulatory drugs targeting CTLA4, given post-operatively to melanoma patients, appear to provide significant benefit." (PMID 28988016, 2017). "Interestingly, while several types of tumors showed positive response, the results of CTLA-4 blockade were most impressive in melanoma." (PMID 28497159, 2017). "Ipilimumab, a monoclonal antibody against CTLA-4, was approved for treating human melanoma in 2011." (PMID 28977985, 2017). "Two recent clinical trials for untreated melanoma using a combination of nivolumab (α-programmed cell death protein-1, α-PD-1) and ipilimumab (α-CTLA-4) reported objective response rates of 53% and 61%, with complete responses seen in 11.5% and 22% of patients." (PMID 29072624, 2017). "In a syngeneic murine model of malignant melanoma, the targeted, localized delivery of anti-CTLA-4 and anti-PD-L1 antibodies to the TME via an oncolytic measles virus induced comparably robust antigen-specific antitumor immune responses without evidence of immune-mediated toxicity." (PMID 28589085, 2017). "In the current landscape, superior response rates observed with BRAF/MEK inhibitors and PD-1/CTLA-4 inhibitors have resulted in these agents supplanting HD IL-2 in the treatment of melanoma patients; particularly when coupled with the attendant complexities of HD IL-2 administration." (PMID 28923120, 2017). "El bloqueo de puntos de control inmunológicos immune-checkpoints con anticuerpos monoclonales dirigidos contra receptores que normalmente inhiben el sistema inmune, como CTLA-4 o PD-1, ha resultado ser un tratamiento exitoso para pacientes con melanoma avanzado." (PMID 29213157, 2017). "Indeed, in melanoma, recent studies indicate significant enhancement of activity of PD-1 blockade when combined with CTLA-4 blockade, an effect that was primarily seen in patients with PD-L1-non-expressing tumours." (PMID 28194010, 2017). "Interestingly, in an animal model of melanoma, CTLA-4 inhibition resulted in a higher proportion of TIL expressing PD-1 while PD-1 inhibition led to increased TIL expression of CTLA-4." (PMID 29179523, 2017).
melanoma (continued). "Therapeutic agents such as ipilimumab, which targets the cytotoxic T lymphocyte-associated protein 4 (CTLA4), and vemurafenib, which targets mutations that activate the B- Rapidly Accelerated Fibrosarcoma (RAF) gene, have previously been developed for malignant melanoma." (PMID 28178658, 2017). "Thus, the improved immunologic memory observed after vaccination with trAbs combined with CTLA-4 blockade correlated with increased serum titers of melanoma-reactive IgG2a antibodies." (PMID 27966460, 2017). "Ipilimumab (FDA approved for melanoma therapy in 2011), the human monoclonal immunoglobulin G1 against CTLA-4, has been shown to expand anti-tumor T cell activity and inhibit immune tolerance, therefore significantly enhancing the melanoma patients overall survival rate." (PMID 28567163, 2017). "Initial evidence, for example with combined inhibition of PD-1 and CTLA-4 in melanoma and non-small cell lung cancer (NSCLC), has highlighted the potential to further enhance the clinical benefits of monotherapies by combining agents with synergistic mechanisms of action." (PMID 28239469, 2017). "Immune checkpoint inhibitors targeting cytotoxic T-lymphocyte associated protein 4 (CTLA-4) and programmable cell death protein 1 (PD-1)/PD-L1 have shown antitumor activity in cancers such as melanoma, non-small cell lung cancer, renal cell carcinoma, and urothelial cancer." (PMID 29250474, 2017). "From a clinical perspective of the treatment of BRAF‐mutated melanomas, this synergism could be exploited with either immune‐checkpoint modulators (Anti‐PD1 Ab or Anti CTLA‐4) or with approaches based on adoptively transferred antitumor lymphocytes." (PMID 27974353, 2017). "Intriguingly, LRBA deficiency and CTLA4 haploinsufficiency could represent human in vivo models of CTLA4 blockade with checkpoint inhibitors; medicines that actually improved survival in several cancers, particularly in melanoma, but also in gastric cancer." (PMID 28720148, 2017). "Moreover, our study shows that detectable levels of CD137 on circulating CD8+ T cells after LN or metastatic resection in stage IIIc and IV melanoma tends to predict longer PFS for the anti-CTLA-4 + anti-PD-1 co-blockade." (PMID 28928380, 2017). "Indeed, TCR diversity was associated with good clinical outcomes following treatment with the MAb ipilimumab targeting CTLA-4 in a small series of melanoma patients." (PMID 28100240, 2017). "In melanoma, flow cytometry was applied to study mechanisms of effects of immunotherapies, such as a PD-1 protein blockade by monoclonal antibodies pembrolizumab or nivolumab, CTLA-4 blockade with ipilimumab or high-dose IL-2 therapy." (PMID 29236046, 2017). "Although CTLA-4 blockade has not been as extensively studied in hematologic malignancies, ipilimumab, an anti-CTLA-4 inhibitor approved for use in melanoma, was studied in a phase 1/1b study of patients with relapsed disease after allogeneic stem cell transplant." (PMID 28434396, 2017). "Combination of anti-PD1 and anti-CTLA-4 inhibitors demonstrated superior response rates compared with monotherapy in advanced melanoma, as well as in advanced NSCLC in a few early phase trials, with ongoing cohort expansion and phase III trials for confirmation of activity pending." (PMID 29258618, 2017). "The pronounced clinical activity of checkpoint inhibitors including antibodies directed against CTLA-4, PD-1 and PD-L1 has transformed the care of several cancers including melanoma, renal cell carcinoma, NSCLC, bladder cancer, head and neck cancer, Hodgkin lymphoma, and others." (PMID 28239469, 2017). "Specifically, it remains to be shown whether PD-L1 negative patients should be treated concurrently with an anti-CTLA-4 antibody (such as ipilimumab or tremelimumab) as appears to be the evolving strategy for melanoma." (PMID 27532023, 2016). "However, little literatures reported expressions of CTLA-4 in cancers including lung cancers, head and neck cancers, melanoma and liver cancers." (PMID 27602763, 2016).
melanoma (continued). "Two anti-CTLA-4 antibodies, ipilimumab (Yervoy®, Bristol-Myers Squibb) and tremelimumab, (CP-675,206, Astra-Zeneca) have been assessed in gastroesophageal cancer, the former is licensed for use in melanoma." (PMID 27669318, 2016). "In combination anti-PD-1 and anti-CTLA-4 in B16 melanoma, reduced treatment efficacy was observed when MDSCs were recruited via IDO overexpression (B16-IDO) by the tumor and blocking MDSCs recruitment via CSF-1R blockade improved efficacy in B16-IDO but not in B16." (PMID 28031817, 2016). "In addition, overexpression of CTLA-4 has been found in several malignant cancer cell lines including melanoma, colon cancer, breast cancer, neuroblastoma, and osteosarcoma, which produces an opportunity for targeted therapy." (PMID 28536390, 2016). "Ipilimumab is an FDA-approved human monoclonal antibody that blocks an immune checkpoint molecule called cytotoxic T-lymphocyte-associated antigen 4 (CTLA-4) leading to increased antitumor activity of tumor-specific T-cells and improved survival in patients with melanoma." (PMID 26881150, 2016). "Likewise, AZA appears to augment CTLA-4 expression in a murine model of melanoma through similar mechanisms." (PMID 27854240, 2016). "However, in preclinical studies of melanoma, combined targeting of CTLA-4 and PD-1 more than doubled the rate of tumor rejection and increased tumor-infiltrating T-cells while reducing Tregs and MDSCs in the TME." (PMID 31093342, 2016). "Dual checkpoint inhibition through CTLA-4 and PD-1/PD-L1 blockade has been evaluated in melanoma." (PMID 27703409, 2016). "Both Cytotoxic T-Lymphocyte Antigen-4 (CTLA-4) and Programmed Death-1 (PD-1) are receptors that dampen T cell responses, and blocking these receptors with antibodies is approved for patients with advanced melanoma to enhance its recognition and elimination." (PMID 28018236, 2016). "Preclinical studies showed that subcutaneous injection of GVAX plus CTLA-4 blockade synergistically promoted tumor eradication in the B16 mouse melanoma model (response rate 80 versus 16% with GVAX alone) due to an increase in CD8+ T cells and in effector T cell/Treg ratio in the tumor." (PMID 27847783, 2016). "Targeting the immune checkpoint pathways of CTLA4, PD-1 and PD-L1 has been remarkably successful in melanoma, non-small cell lung cancer (NSCLC) and urothelial cancers, and is currently being investigated extensively in clinical trials for patients with gastroesophageal cancer." (PMID 27669318, 2016). "We find that melanomas expressing high levels of CTLA4 separate into two distinct groups with respect to CD8 T-cell infiltration, which might influence clinical responses to anti-CTLA4 agents." (PMID 27549193, 2016). "Therefore, the combination of anti-VEGF-A (bevacizumab; humanized IgG1, Roche) and anti-CTLA-4 (ipilimumab) was investigated in a phase I trial in advanced melanoma patients." (PMID 27847783, 2016). "We were among the first to report that frequencies and phenotypes of myeloid cells were rapidly altered in response to anti-CTLA-4 blocking antibody Ipilimumab in melanoma patients and could be correlated to poor treatment outcome." (PMID 28123870, 2016). "Finally, PD-1 and CTLA-4 combination blockade expanded infiltrating T cells and reduced regulatory T and myeloid cells within B16 melanoma tumors." (PMID 27917371, 2016). "About 20 % of advanced NSCLC patients and 30 % of advanced melanoma patients experience tumor responses from checkpoint blockade monotherapy, with better clinical responses seen with the combination of anti-PD-1 and anti-CTLA-4 antibodies." (PMID 27234522, 2016). "Ipilimumab, a CTLA-4 antibody, has been studied in melanoma." (PMID 27118383, 2016). "Indeed, combined blockade of CTLA-4 and PD-1 prolonged survival in a B16 melanoma model, and combined PD-L1 and CTLA-4 blockade prolonged disease-free survival in the K7M2 model for metastatic osteosarcoma." (PMID 27847783, 2016).